CX3CR1 (C-X3-C motif chemokine receptor 1)
Diseases named in the same sentence as CX3CR1 in open-access papers (continued):
Sharing a sentence is not in itself a finding about the gene and the disease.
breast carcinoma (continued). "Activation of FGFR1 on breast cancer cells, as well as on stromal cells in the TME, initiates the production of the chemokine CX3CL1 (fractalkine) that recruits CX3CR1-expressing macrophages/monocytes to the TME." (PMID 35677046, 2022). "In a murine model of breast cancer, the induction of CX3CL1 seemed to increase the infiltration of CX3CR1+ macrophages into the tumor, as well as the vascularization of the tumor." (PMID 33391453, 2021). "Examination of breast cancer specimens of luminal A, luminal B, HER2 and TNBC subtypes all indicated comparable expression of CX3CR1." (PMID 34066014, 2021). "The activation of CX3CR1 activates multiple signaling pathways, in particular the Src → FAK pathway in breast cancer cells, lung cancer cells, pancreatic ductal adenocarcinoma cells and in prostate cancer cells." (PMID 32466280, 2020). "The CX3CR1/CX3CL1 and CXCR3/CXCL10 axes have been demonstrated to be involved in the proliferation, survival, and metastasis of various malignant tumor types, including breast cancer, and were suggested to predict the site of metastatic relapse." (PMID 31026363, 2019). "Tumors of nonneuronal origin, for example, prostate, pancreas, and breast cancer, show overexpression of CX3CR1 that regulates adhesion and migration of tumor cells to metastatic sites." (PMID 24799766, 2014). "In addition to studying CX3CL1, previous studies have examined expression of CX3CR1 on breast cancer cells and the autocrine effects of the CX3CL1/CX3CR1 axis on regulating breast cancer cell migration." (PMID 23029290, 2012). "Based on our study, it seems reasonable to propose that the dissemination to the skeleton of breast cancer cells can be effectively counteracted by interfering with the molecular and functional interactions between the chemokine FKN and its only receptor CX3CR1." (PMID 21933397, 2011). "Also, 7 breast cancer cell lines, 12 melanoma cell lines tested and their normal counterparts (mammary epithelial cells and melanocytes) do not express CX3CR1." (PMID 24789099, 2014). "Moreover, recent studies indicate a role for CX3CR1/CX3CL1 in mediating cross-talk between tumor cells and their surrounding microenvironment in models of lymphocytic leukemia, glioblastoma, neuroblastoma, pancreatic cancer, prostate cancer, and breast cancer." (PMID 23029290, 2012). "The screening results showed that none of the receptors for Cx3cl1 (CX3CR1), Cxcl16 (CXCR6), Ccl17 (CCR4, DARC, CCR10) or IL6 (IL6R) was more expressed in basal B compared to basal A or luminal breast cancer cells." (PMID 38055067, 2023).
Parkinson disease (33 papers, 2009 to 2025). A progressive degenerative disorder of the central nervous system characterized by loss of dopamine producing neurons in the substantia nigra and the presence of Lewy bodies in the substantia nigra and locus coeruleus. "CX3CR1 deficiency dysregulates microglial responses and causes more extensive neuronal cell loss, resulting in neurotoxicity in a toxic model of Parkinson’s disease (PD) and a transgenic model of amyotrophic lateral sclerosis." (PMID 31727112, 2019). "In models for Parkinson’s disease (PD) under a CX3CR1-deficient background, microglia exhibit an over-activated phenotype and neuronal cell death is enhanced." (PMID 28690540, 2017). "On the other hand, loss of CX3CR1 exaggerates neuron apoptosis in Parkinson's disease, amyotrophic lateral sclerosis, and encephalomyelitis." (PMID 22536384, 2012). "For instance, CX3CR1 deficiency dysregulates microglial responses, resulting in neurotoxicity in models of Parkinson's disease and amyotrophic lateral sclerosis." (PMID 22536384, 2012). "Recent studies have shown that CD38 on Plasma Blast-Plasma cells was associated with a lower risk of Parkinson’s disease, CX3CR1 on CD14- CD16- monocytes was associated with a lower risk of developing cerebral aneurysms and was associated with a higher risk of chronic pancreatitis." (PMID 40328660, 2025). "In a mouse model of Parkinson’s disease, CX3CR1−/− mice showed more pronounced cell death in the pars compacta of the substantia nigra than did CX3CR1+/+ mice, and similar results were obtained for CX3CL1−/− mice." (PMID 39062768, 2024). "While the levels of CX3CR1 exhibit complex, even opposite, changes in Parkinson Disease (PD), the levels of FKN increase in PD, and the ratio of FKN to Aβ has been positively correlated with PD severity and progression." (PMID 36644710, 2023). "In line with this, increased CX3CR1 signaling was found to be neuroprotective by reducing microglial activation in experimental models of Parkinson’s disease models and proteinopathies." (PMID 34838047, 2021). "CX3CR1-null mice have worse functional outcomes after models of Parkinson’s disease, amyloid lateral sclerosis, and LPS-induced neuroinflammation." (PMID 25469644, 2014). "It has been suggested that the expression of CX3CR1 has beneficial neuroprotective and neuronal survival consequences in animal models of systemic inflammation, Parkinson disease and amyotrophic lateral sclerosis." (PMID 19865478, 2009). "Parkinson’s disease mouse model for investigation of microglial CX3CR1." (PMID 41424797, 2025). "Microglial activation has been linked to retinal degeneration in CNS disorders and others like Alzheimer’s, Parkinson’s, and Huntington’s diseases; therefore, the number of CX3CR1-positive microglia was evaluated in vivo using cSLO over a period of six weeks following HHI-LI-PRL." (PMID 37638037, 2023). "The deletion of CX3CR1 expression could promote microglial activation, and enhancement of CX3CR1 expression could protect against microglial neurotoxicity in the model of Parkinson’s disease and a transgenic model of amyotrophic lateral sclerosis." (PMID 32403417, 2020). "Indeed some authors showed that CX3CL1/CX3CR1 had a neuroprotective role in a rat Parkinson’s disease model and prevented oxidative stress in murine glial and neuronal cells in vitro." (PMID 30092003, 2018). "CX3CR1-null mice are said to display microglial hyper-activation but its role is apparently damage-dependent because CX3CR1 deletion was beneficial in models of transient ischemia and Alzheimer’s but harmful in Parkinson’s and ALS models." (PMID 28830445, 2017). "It is worthy to note that Cx3cr1‐Cre can sometimes evince haploinsufficiency in mouse models under pathological conditions, including LPS‐ or acute injury‐induced systemic inflammation, MPTP‐induced parkinsonism and the SOD1G93A model of amyotrophic lateral sclerosis." (PMID 36878712, 2023).
Parkinson disease (continued). "Mice lacking CX3CR1 develop increased disease severity in animal models of experimental autoimmune encephalomyelitis (EAE), low-endotoxemia, Parkinson’s disease, Amyotrophic lateral sclerosis, and Diabetic retinopathy." (PMID 31263398, 2019). "In contrast, expression of homeostatic markers such as CX3CR1 and TGFBR1, as well as MERTK were unaffected by in vitro α-syn PFF exposure, suggesting α-syn fibrils are direct drivers of some, but not all, microglial transcriptomic changes in late-stage Parkinson’s disease/Lewy body dementia." (PMID 37671615, 2024).
amyotrophic lateral sclerosis (32 papers, 2009 to 2025). Amyotrophic lateral sclerosis (ALS) is a neurodegenerative disease characterized by progressive muscular paralysis reflecting degeneration of motor neurons in the primary motor cortex, corticospinal tracts, brainstem and spinal cord. "CX3CR1 deficiency also accelerates neurodegeneration in mouse models of Parkinson's disease (PD) and Amyotrophic Lateral Sclerosis (ALS)." (PMID 26089772, 2015). "Amyotrophic lateral sclerosis patients who carry one or two copies of the CX3CR1-Val249Ile allele experience a more rapid disease progression and shorter survival than those with wild-type Cx3cr1." (PMID 39940727, 2025). "The objective of this study was to investigate the association of functional variants of the human CX3CR1 gene (Fractalkine receptor) with the risk of Amyotrophic Lateral Sclerosis (ALS), the survival and the progression rate of the disease symptoms in a Spanish ALS cohort." (PMID 24806473, 2014). "CX3CR1 deficiency could also induce dysregulation in the autophagy–lysosome degradation pathway and impair the autophagosome maturation process in mice with amyotrophic lateral sclerosis." (PMID 34683104, 2021). "For instance, in animal models of Parkinson's disease and amyotrophic lateral sclerosis (ALS), loss of CX3CR1 increased neuronal cell death." (PMID 30245686, 2018). "For instance, microglia expressing CX3CR1 or CD11c have been implicated in AD pathology, while microglial expression of 5D4-KSPG and CCl4 is associated with amyotrophic lateral sclerosis and aging, respectively." (PMID 40307569, 2025). "Dysregulated microglia-mediated neurotoxicity upon CX3CR1 deficiency is also known in central nervous system (CNS)-related conditions, such as CNS response to systemic endotoxin-induced inflammation, Parkinson's disease, and amyotrophic lateral sclerosis (ALS)." (PMID 32265903, 2020). "It was shown that microglia uniformly downregulate their homeostatic signature genes, such as Sall1, Pu.1, Tmem119, Cx3cr1, and P2ry12/13 and upregulate risk genes for AD, such as Apoe and Trem2, in mouse models for aging, AD (5XFAD and APP-PS1), and amyotrophic lateral sclerosis (ALS) (SOD1)." (PMID 30108586, 2018). "In mouse models of other neurodegenerative disease such as Parkinson’s disease or ALS (amyotrophic lateral sclerosis), lack of CX3CR1 causes widespread neuron loss, suggesting that the microglial activation profile seen here is an AD-specific effect." (PMID 24490742, 2014). "In a murine model of amyotrophic lateral sclerosis, the absence of CX3CR1 accelerates the progression of the disease, leading to rapid and increased neuronal cell death." (PMID 39940727, 2025). "Similarly, CX3CR1 knockout also accelerates disease progression in the G93A mutant Cu, Zn-superoxide dismutase (SOD1) mouse model of amyotrophic lateral sclerosis." (PMID 32410624, 2020). "Broadly, they found that microglia lacking CX3CR1 are cytotoxic in models of systemic inflammation, amyotrophic lateral sclerosis (ALS), and Parkinson’s disease (PD)." (PMID 30744705, 2019). "In an amyotrophic lateral sclerosis model, lack of CX3CL1/CX3CR1 signal in the CNS activates the NF-κB pathway, with increased microglia activation and neuronal damage." (PMID 37234914, 2023).
diabetes (32 papers, 2008 to 2026). "In the diabetic murine retina, genetic and pharmacological inhibition of CX3CR1-FKN signaling inhibited diabetes associated vaso-constriction." (PMID 37033925, 2023). "In a murine model of streptozotocin-induced diabetes, CX3CR1 deficiency decreased extracellular matrix deposition." (PMID 34009468, 2021). "Cx3cr1 deficiency in mice leads to a strong increase of subretinal MP accumulation with age, after light challenge or laser injury, in diabetes and in a paraquat-induced retinopathy model." (PMID 25604058, 2015). "Finally, monocyte subset frequency and CX3CR1 expression was positively associated with dementia, while negatively associated with anemia and diabetes in the advanced-age, frail elderly." (PMID 25105870, 2014). "Furthermore, the CX3CR1 signaling pathway is intricately linked to the generation of various cytokines, offering novel perspectives for potential therapeutic interventions in the context of diabetes combined with MAFLD." (PMID 40918148, 2025). "Research indicates that CX3CR1 deficiency or dysfunction could exacerbate liver damage associated with diabetes, underscoring its significant contributory role in the development of diabetes combined with MAFLD." (PMID 40918148, 2025). "In contrast, reductions in CX3CR1 expression only occurred in the advanced-age, frail elderly and individuals with elevated levels of CX3CR1 had a greater likelihood of having dementia, while reduced expression was associated with an increased risk of diabetes and anemia." (PMID 25105870, 2014). "The potential to target the CX3CL1/CX3CR1 axis via therapeutic intervention at the level of the placenta in PE- and diabetes-complicated pregnancy is the subject of ongoing research." (PMID 41683599, 2026). "To better understand the role of CX3CR1-variants in microglia-mediated inflammation, we utilized LPS-induced low-level endotoxemia and STZ-induced diabetes, as a two-hit model of diabetes and systemic inflammation." (PMID 37033925, 2023). "FKN acts as a regulator of inflammation and iron metabolism via controlling the downstream signalling cascades mediated by FKN/CX3CR1 interaction and it appears to work as a link between diabetes, inflammation, and iron metabolism." (PMID 36210435, 2022). "Treatment with the ACE-inhibitor temocapril reduced intra-renal mRNA and protein levels of CX3CL1 and CX3CR1 eight weeks after induction of diabetes." (PMID 34163473, 2021). "A multivariable regression model showed that CX3CR1 expression on lymphocytes is an independent predictor of death from acute melioidosis, when controlling for age, sex, diabetes status, and preexisting renal disease." (PMID 31032897, 2019). "Taken together, our results demonstrate a population of CD57+CX3CR1+GPR56+ co-expressing predominantly CD4+ TEMRA cells in both blood and SAT of PLWH which appear to be associated with diabetes." (PMID 30941121, 2019). "CX3CR1 expression on lymphocytes was identified as a novel correlate of survival from acute melioidosis when considering all patients and controlling for diabetes." (PMID 31032897, 2019). "To investigate further the emerging role of the fractalkine pathway in diet-induced insulin resistance, glucose homeostasis and diabetes, we undertook detailed metabolic phenotyping in the Cx3cr1-/- mouse model." (PMID 26393344, 2015). "Little is known regarding monocyte phenotype or CX3CR1 expression and diabetes, although it has been shown that monocytes display an activated phenotype in diabetics and the production of CX3CL1, likely by adipocytes, is found at higher levels in diabetics." (PMID 25105870, 2014). "In conclusion, it is very likely that increased CX3CL1 concentration in diabetes class C, together with the upregulation of its specific and sole receptor, CX3CR1, are involved in the pathomechanism of placental microvasculature remodeling." (PMID 23956503, 2013).
diabetes (continued). "The mean concentration of CX3CL1 in diabetes was increased and accompanied by augmented placental microvessel density as well as a higher expression of CX3CR1." (PMID 23956503, 2013). "The higher expression of CX3CR1 in diabetes corresponded to the augmentation of the placental vascularization, as assessed by V/EVTI." (PMID 23956503, 2013). "The mean percentage value of CX3CR1 expression estimated in the vascular density-matched samples was remarkably higher (P < 0.01) in diabetes and reached 235.2 ± 24.4 (%, ±SEM) of the reference value established in group II." (PMID 23956503, 2013). "In conclusion, we suggest involvement of CX3CL1/CX3CR1 signaling pathway in the pathomechanism of placental microvasculature remodeling in diabetes class C." (PMID 23956503, 2013). "Modulators of CX3CR1 can be used to treat diabetes, as well as diagnose diabetes by measuring the levels of CX3CR1 in a patient (US patents 2006)." (PMID 18570670, 2008). "In diabetes mellitus combined with metabolic-associated fatty liver disease (MAFLD), aberrant expression and function of CX3CR1 might relate to inflammatory responses and impaired lipid metabolism." (PMID 40918148, 2025). "In addition, samples with low expression of CX3CR1 were mainly enriched in “fatty acid biosynthesis”, “maturity onset diabetes of the young”, and “mitophagy”." (PMID 38245687, 2024). "Accordingly, inhibition of the CX3CL1/CX3CR1 system by neutralizing antibody of CX3CL1 or silencing of CX3CR1 or SGLT2i may represent a novel therapeutic strategy for improving cardiorenal dysfunction in diabetes." (PMID 35370759, 2022). "Taken together, it seems that CX3CL1/CX3CR1 system may play an important role in cardiorenal crosstalk via circulating sCX3CL1 in diabetes." (PMID 35370759, 2022). "Thus, the blood glucose level was regulated by CX3CR1-related pathways in the diabetes models and T2DMC group." (PMID 36072409, 2022). "Therefore, even though diabetes, depression, and DD regulate secretion of DA, 5-HT, and NA, CX3CR1 blocker treatment modulates the secretion of the three monoamine neurotransmitters in DD rats." (PMID 36072409, 2022). "Interestingly, diabetes alone promoted a significant effect on microglial morphology as revealed by the data comparing CX3CR1-HET and Akita-HET mice." (PMID 28119571, 2016). "Ins2Akita and streptozotocin (STZ) induced diabetes models, associated with insulin misfolding or deficient pancreatic β-islet cells, respectively, showed that in absence of CX3CR1 (CX3CR1KO), retinas displayed enhanced microglia activation, neuronal loss, and astrogliosis." (PMID 38311721, 2024). "However, Glu and D-serine levels in DD group were significantly enhanced than those in depression and diabetes group (P < 0.05, P < 0.01); CX3CR1 blocker treatment of DD group significantly reduced the levels of Glu and D-serine in hippocampus all group (P < 0.05, P < 0.01)." (PMID 36072409, 2022). "However, TNF-α, IL-1B, and IL-6 secretion in DD group was significantly enhanced than that in depression and diabetes group (P < 0.05, P < 0.01); CX3CR1 blocker treatment of DD group significantly reduced the levels of TNF-α, IL-1B, and IL-6 in hippocampus of all groups (P < 0.05, P < 0.01)." (PMID 36072409, 2022). "Similarly, reduced expression of the fractalkine receptor gene Cx3CR1 was evident in retinal microglia during diabetes compared to those from the cortex, a change that in addition to impairment of “find me” signal detection could have proinflammatory effects in the microglial cells." (PMID 40940761, 2025). "Pathways commonly activated by diabetes-related conditions include NF-κB, NLRP3 inflammasome, fractalkine/CX3CR1, MAPKs, AGEs/RAGE and Akt/mTOR." (PMID 36869375, 2023). "In this study we examined comparatively (diabetes class C complicated versus normal pregnancy) the correlation between CX3CL1 content in placental tissue, the mean CX3CR1 expression, and density of the network of placental microvessels." (PMID 23956503, 2013).